APOBEC3B (apolipoprotein B mRNA editing enzyme catalytic subunit 3B)
Diseases named in the same sentence as APOBEC3B in open-access papers (continued):
Sharing a sentence is not in itself a finding about the gene and the disease.
invasive breast carcinoma (3 papers, 2016 to 2022). A carcinoma that infiltrates the breast parenchyma. "The high load of C/G mutations in invasive breast cancer likely reflects damages caused by APOBEC3B-induced U/G mismatches and AP-sites at C/G base pairs as well as other G/C base damages." (PMID 26926109, 2016). "The association between APOBEC3B mRNA expression and the patient prognosis was examined in 295 invasive breast cancer patients.The median follow-up period was 4.93years (range, 0.5–19.9 years)." (PMID 27977754, 2016). "Independently, mutation analyses in human invasive breast cancer confirmed a pro-mutagenic activity of APOBEC3B and revealed a genome-wide anti-mutagenic activity of PRIMPOL as well as most Y-family TLS polymerases." (PMID 26926109, 2016). "As suggested previously, C deamination by APOBEC3B predominantly generates C>T transitions, and in invasive breast cancer this is the most abundant point mutation." (PMID 26926109, 2016). "Similar to the processing of AID-induced DNA lesions during SHM, APOBEC3B expression was also found to correlate with mutations at template A/T in invasive breast cancer." (PMID 26926109, 2016). "In testicular germ cell tumors and invasive breast carcinomas, APOBEC3B expression and CD8+ T lymphocyte counts were correlated." (PMID 35918642, 2022). "In contrast to all other family members, POLH expression showed a positive pro-mutagenic correlation with both C and TpC transversions, suggesting an involvement of POLH in bypassing APOBEC3B-induced AP-sites in invasive breast cancer." (PMID 26926109, 2016). "This also accounted for TpC>G and TpC>A mutations, indicating that POLH contributes to the increased TpC>G and TpC>A transversions in APOBEC3B expressing invasive breast cancers." (PMID 26926109, 2016). "However, the difference between murine SHM and APOBEC3B mutagenesis in human invasive breast cancer is that PRIMPOL affects C/G transversions and transition in invasive breast cancer, whereas only C>G transversion are affected by PrimPol in our SHM readout." (PMID 26926109, 2016).
oral squamous cell carcinoma (3 papers, 2017 to 2022). "The frequency of APOBEC3B-deletion alleles is ~50% in 143 genotyped oral squamous cell carcinoma -Taiwan samples (27A3B−/−:89A3B+/−:27A3B+/+), compared to the 5.8% found in 314 OSCC-TCGA samples." (PMID 28878238, 2017). "We thus report a frequent APOBEC mutational profile, which relates to a APOBEC3B-deletion germline polymorphism in Taiwanese oral squamous cell carcinoma that impacts expression of APOBEC3A, and is shown to be of clinical prognostic relevance." (PMID 28878238, 2017). "Interestingly, presence of the APOBEC3B deletion allele was found to be associated with higher levels of APOBEC3 DNA editing in oral squamous cell carcinoma samples, indicating that this genetic polymorphism does affect APOBEC3 mutation rates in vivo." (PMID 36146883, 2022). "X-Irradiation induced APOBEC3B expression in HepG2, human cervical cancer epithelial carcinoma (HeLa) and human oral squamous cell carcinoma (SAS) cells." (PMID 32880638, 2020).
serous ovarian cancer (3 papers, 2015 to 2018). "Due to the expression data and mutation patterns, it was suggested that APOBEC3B lesions are processed error prone and also attribute APOBEC3B a potential role in genomic instability in serous ovarian cancer." (PMID 26097867, 2015). "Using a discovery cohort of 194 high‐grade serous ovarian adenocarcinoma (HGS‐OvCa) exomes, the results confirm the ability of the novel in silico approach used to identify changes in the preferred target motifs for AID, APOBEC3G, APOBEC3B, and ADAR1 during oncogenesis." (PMID 27485054, 2016).
urothelial carcinoma (3 papers, 2018 to 2022). A malignant neoplasm derived from the transitional epithelium of the urinary tract (urinary bladder, ureter, urethra, or renal pelvis). "Metastatic urothelial carcinomas often harbor APOBEC3B-mediated mutations in which tCw to T or G substitution occurs." (PMID 33925044, 2021). "Therefore, besides cytotoxic chemotherapy, further studies are needed to evaluate the influence of APOBEC3B mutation on ICIs in urothelial carcinoma." (PMID 33925044, 2021). "Second, there is a lack of basic research to logically support our finding that HPV infection can promote the occurrence of urothelial carcinoma by upregulating the expression of APOBEC3B and HPV E6 protein." (PMID 35903294, 2022). "Meanwhile, APOBEC3B was highly expressed in patients with stage I (χ2 = 4.057, P = 0.044) and low-grade urothelial carcinoma (χ2 = 7.153, P = 0.007)." (PMID 35903294, 2022).
adenovirus infection (2 papers, 2022 to 2023). "Importantly, we show that adenovirus infection leads to a reduction of the quantity and/or enzymatic activity of the APOBEC3B protein depending on the strains." (PMID 36745676, 2023).
AIDS (2 papers, 2014 to 2023). A syndrome resulting from the acquired deficiency of cellular immunity caused by the human immunodeficiency virus (HIV). "Homozygous deletion of APOBEC3B was significantly associated with unfavorable outcomes for HIV-1 acquisition and progression to AIDS." (PMID 25502777, 2014).
clear cell ovarian cancer (2 papers, 2021 to 2022). "For example, APOBEC3B was found to express higher in patients with improved survival in clear cell ovarian cancer (CCOC), which was also expected to be a promising biomarker for forecasting the effect to platinum-based therapy." (PMID 34745121, 2021).
esophageal squamous cell carcinoma (2 papers, 2015 to 2019). Esophageal squamous cell carcinoma (ESCC) is a type of esophageal carcinoma (EC) that can affect any part of the esophagus, but is usually located in the upper or middle third. "C:G>T:A transitions at TpCpX sequences represent the involvement of APOBEC3B in the development of esophageal squamous cell carcinoma, consistent with the fact that APOBEC3B expression is upregulated in these tumors." (PMID 26083936, 2015).
gynecological cancers (2 papers, 2023 to 2025). "On the other hand, we found that APOBEC3B was associated with the pathway of cell cycle in all these three common gynecologic cancers." (PMID 39944833, 2025). "In conclusion, our findings indicate that the expression of 6-CRRGs, including APOBEC3B, HELLS, SLC15A3, CDA, RHOB and UPP1, is associated with the prognosis of patients with common gynecological cancers." (PMID 39944833, 2025). "Previous studies have documented the overexpression of APOBEC3B in gynecological cancer." (PMID 39944833, 2025).
liver cancer (2 papers, 2022 to 2023). An epithelial or non-epithelial malignant neoplasm that arises from the liver. "Studies have reported that APOBEC3B also mutates the HBX protein of HBV to promote the development of liver cancer." (PMID 36203448, 2022). "The present, review of the molecular mechanisms associated with APOBEC3B in liver cancer provides a new possibility for these mechanisms." (PMID 36203448, 2022). "Scientists have also speculated whether APOBEC3B promotes the development of liver cancer by mutating the genome of liver cells, but previous studies have reported lack of mutation patterns of APOBEC3B in liver cancer." (PMID 36203448, 2022). "Thus, it remains unclear whether, the mutation effect of APOBEC3B on HBV promotes liver cancer or inhibits liver cancer." (PMID 36203448, 2022). "We found that ADAR1 was significantly overexpressed in liver cancer patients (≥±1.5-fold, P < 0.05), and APOBEC3B was also significantly upregulated in the same datasets." (PMID 36599932, 2023). "In humans, APOBEC3B has also been reported to be significantly upregulated in liver cancer, but its role in liver cancer is unclear." (PMID 36203448, 2022). "Although there are still few reports of APOBEC3B in the occurrence and development of liver cancer, it has been established that APOBEC3B plays a key role in liver cancer." (PMID 36203448, 2022). "APOBEC3B overexpression promotes the development of liver cancer in vivo and in vitro, while APOBEC3B knockout inhibits the development of liver cancer." (PMID 36203448, 2022). "However, a comparative gene expression analyses of ADAR1 and APOBEC3B using multistage liver cancer datasets showed liver-cancer-specific expression of ADAR1, and a ROC analysis showed that ADAR1 expression was more specific than APOBEC3B to liver cancer." (PMID 36599932, 2023). "However, relatively little has been reported in highly fatal liver cancers, but there are still reports of APOBEC3B upregulation in liver cancer patients, contradicting the restriction of HBV infection and liver cancer by APOBEC3B via degrading the HBV genome." (PMID 36203448, 2022). "Furthermore, APOBEC3B has been reported to be significantly elevated in liver cancer tissues relative to normal tissues, suggesting that it also plays an essential role in the occurrence and development of liver cancer." (PMID 36203448, 2022). "It has been established that APOBEC3B plays a key role in liver cancer." (PMID 36203448, 2022). "The high expression of APOBEC3B in liver cancer has been validated, but it remains unclear whether it is upregulated in liver cancer as a lagging upregulation." (PMID 36203448, 2022). "Therefore, it is important to fully understand the role and molecular mechanisms of APOBEC3B in liver cancer." (PMID 36203448, 2022). "Thus, APOBEC3B has received increasing attention in various cancers, but the role of APOBEC3B in the occurrence and development of liver cancer due to infection with HBV remains unclear." (PMID 36203448, 2022). "Thus, regulating APOBEC3B is a potential treatment strategy for liver cancer." (PMID 36203448, 2022). "However, the role of APOBEC3B in liver cancer remains unclear, thereby requiring further investigation." (PMID 36203448, 2022). "Therefore, further exploration of the role of APOBEC3B in liver cancer is required." (PMID 36203448, 2022). "In this article, we mainly review the latest research on the molecular mechanisms of APOBEC3B in limiting the pathogenesis of HBV infection and liver cancer to provide a new therapeutic direction or target for liver cancer treatment." (PMID 36203448, 2022). "Therefore, the non-enzyme-dependent function that interferes with APOBEC3B inhibits the immunosuppressive microenvironment mediated by a variety of chemokines, thereby inhibiting the occurrence and development of liver cancer." (PMID 36203448, 2022).
liver cancer (continued). "Thus the occurrence of liver cancer may be mediated by treatment with APOBEC3B agonist therapy at the HBV stage by restricting viral replication or inhibiting the development of liver cancer by interfering with the non-enzyme-dependent function of APOBEC3B in the early stages of liver cancer." (PMID 36203448, 2022).
lymph node metastasis (2 papers, 2014 to 2016). "The T/N ratio of the APOBEC3B/β-actin mRNA level was not significantly different in lymph node metastasis (3.871±5.546) and the lymph node metastasis-negative cases (4.278±8.416, P=0.9462)." (PMID 24748981, 2014).
oral cancers (2 papers, 2025). "The highest levels were found in grade II and III oral cancers suggesting that APOBEC3B may be used as a marker for advanced HPV-positive cancers." (PMID 38907809, 2025). "Moreover, APOBEC3B overexpression differentiated HPV-negative low-grade oral epithelial dysplasia, which showed intermediate APOBEC3B expression, from oral cancers." (PMID 38907809, 2025).
pancreas cancer (2 papers, 2014 to 2019). "As expected, we observed that germline APOBEC3A/B deletion was significantly associated with decreased expression levels of the isoform uc003awo (APOBEC3B) across all cancer types at P < 0.05, except for pancreas cancer with a P = 0.14." (PMID 31533728, 2019). "Real-time PCR assay showed that APOBEC3A and APOBEC3B were underexpressed in pancreatic cancer tissues than in morphologically normal operative margin tissues." (PMID 25502777, 2014).
rectum adenocarcinoma (2 papers, 2022). An adenocarcinoma arising from the rectum. "However, in colon adenocarcinoma (COAD), rectum adenocarcinoma (READ), and thyroid carcinoma (THCA), the expression level of APOBEC3B was significantly lower than that in adjacent normal tissues." (PMID 36249021, 2022).
squamous cell carcinoma (2 papers, 2014 to 2015). A carcinoma arising from squamous epithelial cells. "Addition evidences suggested that APOBEC3B is involved in mutagenesis of human cancers such as bladder, cervix, lung (adenocarcinoma and squamous cell carcinoma), head and neck as well as BC." (PMID 26261799, 2015). "The involvement of APOBEC3B activity in cancer was further supported by data on Ref-seq APOBEC3B expression, which was shown to be high in several tumor types, including breast, uterus, bladder, head and neck and lung (both adenocarcinoma and squamous cell carcinoma)." (PMID 24705290, 2014).
thyroid carcinoma (2 papers, 2022). "Furthermore, the APOBEC3B (A3B) mutational signature is enriched in various cancer types, including the bladder, breast, cervical, and thyroid cancers." (PMID 36245972, 2022).
adrenocortical tumors (1 paper, 2020).
B cell lymphomas (1 paper, 2018). "UNG expression was negatively correlated with APOBEC3B expression in mature B cell lymphoma cell lines (MATBCL; ρ = − 0.372, padj = 0.034, n = 60, Ntests = 230) and with APOBEC3A expression in chronic lymphocytic leukemia cells (CLLE; ρ = − 0.324, padj = 0.037, n = 78, Ntests = 230)." (PMID 29642934, 2018).
cholangiocarcinoma (1 paper, 2023). A carcinoma that arises from the intrahepatic biliary tree (intrahepatic cholangiocarcinoma) or from the junction, or adjacent to the junction, of the right and left hepatic ducts (hilar cholangiocarcinoma). "In contrast, the same SNP rs2267401 was associated with decreased risk of cholangiocarcinoma and lower APOBEC3B promoter activity in this tumor type, likely due to overexpression of the transcriptional repressor TFAP2A." (PMID 36978147, 2023). "Corroborating these findings, a study of cholangiocarcinoma and gallbladder cancer found upregulation of both APOEBC3A and APOBEC3B with IL-6 and TNF-α exposure." (PMID 36978147, 2023).
co-infections (1 paper, 2021). "Overall, studies on the role of the APOBEC3B deletion polymorphism in the susceptibility to HIV acquisition, rates of co-infections, and disease progression have returned different results." (PMID 34372572, 2021).
colorectal cancer (1 paper, 2022). A primary or metastatic malignant neoplasm that affects the colon or rectum. "Consequently, the reduced level of APOBEC3B in colorectal cancer may contribute to the accumulation of LINE-1 copies not through lessened DNA demethylase activity but through decreased restriction of retrotransposons’ mRNA." (PMID 35655145, 2022).
endometrial cancer (1 paper, 2019). Primary or metastatic malignant neoplasm involving the endometrium (mucous membrane that lines the endometrial cavity).
HCMV infection (1 paper, 2023). "Although HCMV infection causes APOBEC3B relocalization from the nucleus to the cytoplasm in multiple cell types, the viral RNR (UL45) is not required." (PMID 37565748, 2023). "Here, we show that HCMV infection causes the antiviral factor, APOBEC3B, to relocalize from the nuclear compartment to the cytoplasm." (PMID 37565748, 2023). "This knowledge is important because a greater understanding of this mechanism could lead to novel antiviral strategies that enable APOBEC3B to naturally restrict HCMV infection." (PMID 37565748, 2023).
kidney cancer (1 paper, 2019). Primary or metastatic malignant neoplasm involving the kidney. "Likewise, an additional association for uc011awn (APOBEC3A) was observed in thyroid, while associations for uc003awo (APOBEC3B) were observed in stomach, pancreas and kidney cancers." (PMID 31533728, 2019). "In comparison with the associations from APOBEC3A, APOBEC3B was specifically associated with APOBEC-mutational signature in stomach, pancreas and kidney cancers, with a P = 5.2 × 10− 11, P = 2.0 × 10− 3, and P = 1.1 × 10− 4, respectively." (PMID 31533728, 2019).
male infertility (1 paper, 2025). The inability of the male to effect fertilization of an ovum after a specified period of unprotected intercourse. "Expression of human APOBEC3B in mice enhances their susceptibility to tumours and also causes male infertility, supporting a pro-tumour role, as well as a detrimental effect on the genetic integrity of the male germline." (PMID 40336011, 2025).
metastatic melanoma (1 paper, 2021). A melanoma that has spread from its primary site to another anatomic site. "In contrast, increased expression was associated with good clinical outcomes in metastatic melanoma except for APOBEC3B and APOBEC3C." (PMID 34638749, 2021).
metastatic prostate carcinoma (1 paper, 2025). A carcinoma that arises from the prostate gland and has spread to other anatomic sites. "Subsequently, the multivariate analysis, focusing on these previously identified significant factors, confirmed T stage, GS, LRP6, LRRK2, PIK3CA, and APOBEC3B deletion as significant predictors of metastatic prostate cancer." (PMID 40660132, 2025). "Key predictors of metastatic prostate cancer identified were T stage, GS, PIK3CA, LRP6, LRRK2, and APOBEC3B deletion." (PMID 40660132, 2025).
neck cancers (1 paper, 2020). "Recent evidence has implicated APOBEC3B (Apolipoprotein B mRNA editing enzyme catalytic subunit 3B) as a source of mutations in breast, bladder, cervical, lung, head, and neck cancers." (PMID 32934779, 2020).
nephritis (1 paper, 2022). Inflammation of renal tissue. "APOBEC3B is upregulated during BKPyV nephritis and has been implicated in the emergence of BKPyV VP1 mutations in kidney transplant recipients and mutations in the Merkel cell PyV genome." (PMID 36341713, 2022).
Nephropathy (1 paper, 2021). A nonspecific term referring to disease or damage of the kidneys. "Four of these strains had a nephropathy-associated mutation, Glu73Gln, attributed to APOBEC3B activity." (PMID 33827948, 2021).
non-alcoholic fatty liver disease (1 paper, 2022). "KEGG data show that the terms ‘thermogenesis’, ‘non-alcoholic fatty liver disease’ and ‘oxidative phosphorylation’ might be involved in the mechanism of APOBEC3B affecting tumorigenesis." (PMID 35918642, 2022).
osteosarcoma (1 paper, 2025). A usually aggressive malignant bone-forming mesenchymal neoplasm, predominantly affecting adolescents and young adults. "PI3K inhibition has previously been shown to reduce APOBEC3B expression in the U2OS human osteosarcoma cell line, via effects on NFκB and AP-1 activity." (PMID 39548236, 2025).
parathyroid carcinoma (1 paper, 2023). "Whether the APOBEC mutational signature and altered expression of APOBEC3B have prognostic value in parathyroid carcinoma requires further investigation." (PMID 37121965, 2023).
renal cell carcinoma (1 paper, 2018). "In contrast, APOBEC3B was reported to be less likely to play a role in mutagenesis of renal cell carcinoma cell lines, suggesting that high prevalence of mutation clusters in the RCC cell lines observed in our study could be generated by molecular factors other than APOBEC3B." (PMID 29642934, 2018).